ERBB2 (erb-b2 receptor tyrosine kinase 2)
Diseases named in the same sentence as ERBB2 in open-access papers (continued):
Sharing a sentence is not in itself a finding about the gene and the disease.
breast cancer (continued). "In the case of breast cancer, PTPRO promoter methylation is a prognostic factor for HER2-positive patients and suppresses ERBB2-driven breast cancer growth by promoting ERBB2 dephosphorylation and endocytotic degradation." (PMID 38182570, 2024). "ERBB2 (also known as HER2) leads to malignancies because of overexpression or amplified, particularly in breast cancer, bladder cancer, lung cancer, ovarian cancer, and so forth." (PMID 38351535, 2024). "FFPE breast cancer samples (n = 170) with routinely assessed HER2 status by IHC/ISH were retrospectively analyzed using the ddPCR CNV ERBB2 assay." (PMID 37996704, 2024). "The metastasis-related gene MMP11 and proliferation-related genes BIRC5, MYBL2, MKI67 (Ki67), AURKA (STK15), CCNB1, and ERBB2 (HER2) from the Oncotype DX gene set exhibit significant up-regulation in tumor samples of breast cancer (BRCA)." (PMID 38254834, 2024). "HER2/ERBB2 overexpression is found in approximately 20% of breast cancers but the standard therapy, the monoclonal HER2 antibody Trastuzumab, fails in one third of the patients." (PMID 38896334, 2024). "To determine the effect of ERBB2 on breast cancer progression, we transfected T47D cells with pcDNA3.1‐NC, pcDNA3.1‐ERBB2, and miR‐449c‐5p mimic+pcDNA3.1‐ERBB2." (PMID 38351535, 2024). "Pyrotinib is an inhibitor of EGFR (ERBB1) and HER2/4 (ERBB2/4), which is approved for the treatment of breast cancer in China." (PMID 39201509, 2024). "For instance, CD44-facilitated ERBB2/3 heterodimer formation serves as a mechanism that has been reported to mediate metastasis in breast cancer models." (PMID 39518076, 2024). "A pivotal player in breast cancer prognosis is the human epidermal growth factor receptor-2 (HER2), also known as Erbb2." (PMID 38920969, 2024). "We investigated the relationship between clinicopathological features of breast cancer and LANR and found that age, TNM stage, positive axillary lymph nodes and human epidermal growth factor receptor 2 (c-erbB2 or HER2) were associated with LANR." (PMID 38766483, 2024). "Our results indicated that the resultant decrease in PFKFB3 expression and activity significantly reduced F26BP and growth in established HER2/Erbb2+ mammary tumors." (PMID 39001392, 2024). "Currently, a phase II clinical trial is underway for the treatment of ER+/ERBB2(HER2)- breast cancer with CFI-402257 and the estrogen receptor-degrading agent Fulvestrant (NCT05251714)." (PMID 39095874, 2024). "Identifying these actionable mutations, which can only be discerned through ERBB2 gene sequencing, also underscores the significance of employing NGS‐based techniques in the care of patient with breast cancer." (PMID 38895905, 2024). "When compared with tissue sections of human Luminal A and HER2 + breast cancers, immunohistochemical analysis of breast ductal adenocarcinomas from Rosa26-RRAS2fl/fl x Wap-Cre mice revealed the lack of ERα, PR, and ErbB2 markers." (PMID 38987766, 2024). "In breast cancer, Nectin-4 and tyrosine kinase receptor ErbB2 (also known as Her2) are highly expressed and can cis-interact with each other to activate the PI3K/AKT signaling pathway for DNA synthesis." (PMID 38606099, 2024). "Lapatinib and trastuzumab are more sensitive to ErbB2-positive breast cancer cells when the laminin-binding integrins (α6β4 integrin and α3β1 integrin) are inhibited in normal culture conditions." (PMID 38279122, 2024). "We observed that the inhibition of tumor growth caused by Pfkfb3 deletion was less marked in the K-rasLA1 lung tumor model relative to the Erbb2 mammary tumor model." (PMID 39001392, 2024). "Over-expression of human epidermal growth factor receptor 2 (HER2/ERBB2) occurs in approximately 20 % of all breast cancers." (PMID 39191139, 2024). "“Black” patients had lower pCR rates for triple-negative and HR−/ERBB2+ breast cancer but higher pCR rates for HR+/ERBB2− breast cancer, whereas “Asians” and “Pacific Islanders” exhibited higher pCR rates for HR−/ERBB2+ malignancies." (PMID 39771527, 2024).
breast cancer (continued). "These drugs have demonstrated significant improvements in patient outcomes in ERBB2-amplified breast cancer patients, and in the case of trastuzumab deruxtecan, are also approved for patients with “HER2-low” disease." (PMID 38406801, 2024). "Its indications include metastatic ErbB2 positive breast cancer, non-small cell lung cancer (NSCLC), and gastric or gastroesophageal junction adenocarcinoma." (PMID 38384285, 2024). "These agents have specific targets in various types of cancer, such as blocking Bruton’s tyrosine kinase (BTK) in mantle cell lymphoma, targeting mutant EGFR in NSCLC, or inhibiting ErbB2 in HER2-positive breast cancer, and Waldenström macroglobulinemia." (PMID 39404419, 2024). "Breast cancer patients express the human epidermal growth factor receptor 2 (HER2 or ERBB2) in around 15%–20% of the cases, which generally present high invasiveness and are associated with poor prognosis." (PMID 38808952, 2024). "Although ERBB2 is best known for its prognostic and predictive roles in breast cancer, studies have also emphasized its prevalence in bladder cancer." (PMID 39410541, 2024). "ErBb2, found on chromosome 17q21, was discovered in the 1980s when human breast cancer showed signs of overexpression." (PMID 39456611, 2024). "Additional research has delved into their relationship at the molecular level, including the impact of Huntington and ErbB2/HER2 signaling on the development and metastasis of breast cancer." (PMID 38702624, 2024). "For instance, monoclonal antibodies targeting ERBB2, such as trastuzumab and pertuzumab, are approved to treat ERBB2-positive breast cancer." (PMID 38713378, 2024). "The goal of this study was to identify genetic factors that control Erbb2-driven mammary tumour development and metastasis using a large cohort of genetically diverse CC mice." (PMID 39067134, 2024). "Sequencing technologies have helped clarify many genomic changes that occur in breast cancer, such as mutations in FOXA1, PIK3CA, ERBB2, and SPOP E78K." (PMID 38193944, 2024). "It has been proposed that SDC, like breast cancer, can be divided into hormone receptor-positive, ERBB2 (HER-2)-positive, and basal-like groups." (PMID 38539538, 2024). "Trastuzumab (Herceptin) binds to the HER2 protein, which is upregulated on certain breast cancer cells, but can also bind to HER2 expressed on cardiomyocytes, interfering with the normal NRG-1/ErbB2 signalling axis resulting in cardiomyocyte apoptosis." (PMID 39081368, 2024). "This is supported by a 5-year survival rate of 85% for individuals diagnosed with stage I breast cancer, which contrasts significantly with the 94% to 99% survival rates reported for hormone receptor-positive and ERBB2-positive patient cohorts." (PMID 39339288, 2024). "The tumor cells from both sexes had similar transcript levels of estrogen receptor alpha (Esr1), androgen receptor (Ar), and human epidermal growth factor receptors (Erbb2, Erbb3), which are the attributes of the Luminal B breast cancer subtype." (PMID 39684829, 2024). "The role of SRC-3 in cancer drug resistance is context-dependent, but previously SRC-3 overexpression has been shown to contribute to Herceptin resistance in ERBB2 overexpressing breast cancer cells." (PMID 38683834, 2024). "HER2-positive breast cancers represent 20% of all breast cancers and are characterized by elevated expression levels of Erb-B2 receptor tyrosine kinase 2 (ERBB2 or HER2)." (PMID 38730603, 2024). "The serine/threonine kinase AKT is frequently hyperactivated in breast cancer through multiple mechanisms, including PI3K activation, PTEN loss, and ErbB2/Her2/neu activation/amplification." (PMID 38722955, 2024).
breast cancer (continued). "ERBB2 amplified tumors are matched to anti-HER2 antibody, trastuzumab, treatment and are classified as tier I-A in breast cancer and are currently investigated in multiple clinical trials in OC patients (e.g. DESTINY: phase 2." (PMID 38519644, 2024). "In contrast, a phase III open-label randomized controlled trial showed that Enhertu (Trastuzumab deruxtecan/T-DXd) was effective in patients with ERBB2 under/over-expressed breast cancer and gastric cancer." (PMID 39060958, 2024). "Overexpression of HER2 and/or amplification of the ERBB2 gene is observed in 15–20% of breast cancer patients and is associated with aggressive disease and a high risk of distant metastases." (PMID 38675107, 2024). "Of note, two HER2-directed antibody-drug conjugates have now been FDA-approved in metastatic ERBB2-amplified breast cancer and are being explored in various other cancer types." (PMID 38406801, 2024). "Patients with ERBB2-overexpressing breast cancer benefit from targeted therapy, such as anti-ERBB2 antibodies." (PMID 39065193, 2024). "In good correspondence with the KRAS G13D mutation and the HER2-low status of the MDA-MB-231 cells, the PROTACs suppress the residual expression of ERBB2, 3 and 4 that are essential for the progress of breast cancer cells." (PMID 38896334, 2024). "We demonstrate that both the LCKD and the MCKD increased FA utilization, critical for ErbB2-positive breast cancer progression, and accelerated the progression of wild-type ErbB2+ tumors." (PMID 39097623, 2024). "TRAF4 can lead to trastuzumab resistance in HER2-positive breast cancer by regulating the ErbB2 signaling pathway." (PMID 39075515, 2024). "HER2 CAR-NK-92 cells manifested specific antitumor cytotoxicity against ErbB2-expressing breast cancer cells in vitro." (PMID 39633491, 2024). "We characterized the impact of factors released from a cell model of ERBB2+ breast cancer on the electrophysiological activity and on the morphology of mature neuronal networks." (PMID 38638322, 2024). "Afatinib is an orally effective epidermal growth factor receptor (EGFR) tyrosine kinase inhibitor (TKI) used in the treatment of ERBB1-mutant lung cancer, and lapatinib has been widely applied in treating ErbB2-overexpressing breast cancer." (PMID 38173048, 2024). "For breast cancer treatment, the identification and quantification of the protein kinase ERBB2 is critical for therapeutic decisions." (PMID 38225548, 2024). "As our comprehension of the molecular underpinnings of ERBB2-positive breast cancer expands, new avenues will open for treatments that are even more patient-specific." (PMID 39067134, 2024). "The different concentrations of resveratrol have bifunctional effects in an estrogen-dependent manner on the ErbB2 levels in human breast cancer cells." (PMID 38673959, 2024). "Human epidermal growth factor receptor 2 (HER2) is encoded by the oncogene ERBB2 and is overexpressed in around 15% of all primary breast cancers." (PMID 38321542, 2024). "In conclusion, our results show that miR‐449c‐5p suppresses breast cancer cell proliferation, invasion and migration by targeting ERBB2 via JAK/STAT signalling pathway." (PMID 38351535, 2024). "Overexpression of ERBB2 is highly related to breast cancer and is observed in 20–30% of all breast cancers." (PMID 38216592, 2024). "ERBB2 is one of the most extensively studied molecules in cancer research, particularly in breast cancer." (PMID 38696425, 2024). "Breast cancer is a significant health concern worldwide, with the amplification of the ERBB2/HER2/Neu gene being a feature found in 20%–30% of cases." (PMID 38638322, 2024). "This study demonstrated that miR‐449c‐5p inhibits breast cancer cell proliferation, migration and invasion by targeting ERBB2 via JAK/STAT, which means miR‐449c‐5p, is a potential biomarker for breast cancer and provides a novel insight for diagnosis." (PMID 38351535, 2024).
breast cancer (continued). "The invasion, migration, and proliferation of breast cancer cells were inhibited by miR‐449c‐5p/ERBB2 through JAK‐STAT." (PMID 38351535, 2024). "The antibody trastuzumab inhibits human epidermal growth factor receptor 2 (HER2/ErbB2) in HER2-positive breast cancer and was one of the first approved targeted therapies in the late 1990s." (PMID 38835346, 2024). "In breast cancers with amplified ERBB2 expression, hyperactivated AKT signaling was associated with the development of resistance to ERBB2 - targeted therapy." (PMID 39268460, 2024). "The amplification of human epidermal growth factor-2 (ERBB2/HER-2), a major proliferation factor and therapeutic target in breast cancer, has been detected in 20–30% of SDC cases and is associated with poor survival." (PMID 38539538, 2024). "Other key examples are amplification of EGFR (7p11.2) in about 40% of glioblastoma cases, ERBB2/HER2 (17q12) in 15–20% of breast cancer cases and MET (7q31) in 1–2% of metastatic colorectal cancer cases." (PMID 38999925, 2024). "HER2-positive (HER2+) breast cancer is characterized by the overexpression of the ERBB2 (HER2) gene, which promotes aggressive tumor growth and poor prognosis." (PMID 39684551, 2024). "ERBB2 gene amplification or protein overexpression serve as dependable biomarkers for guiding anti‐HER2 therapies in breast cancer." (PMID 38895905, 2024). "Then, the gene expression of breast cancer from The Cancer Genome Atlas database (TCGA) showed an upward trend of the expression of ERBB2 in the cancer samples compared with normal samples." (PMID 38351535, 2024). "Especially as the expression of GATA4 in breast cancer inversely correlates with the adverse prognostic marker ERBB2." (PMID 38653973, 2024). "Overall, our data are consistent with the therapeutic potential of a ketogenic diet abundant in LCFAs combined with FAO blockade in ErbB2+ breast cancer." (PMID 39097623, 2024). "Reduced ERBB2 gene amplification in HER2-directed ADC–resistant HER2+ breast cancer cell lines was through DNA damage and epigenetic mechanisms." (PMID 39164784, 2024). "ERBB2+ breast cancer cells secrete EVs, and their number and content are largely modulated by ERBB2+ targeted therapy." (PMID 38638322, 2024). "ErbB2, a member of the ErbB receptor tyrosine kinase family, is observed in up to 30% of primary breast cancers." (PMID 41256008, 2024). "Previous studies have identified concomitant focal amplification of CCNE1 and ERBB2 in gastric cancer as well as breast cancer." (PMID 38717153, 2024). "SCD: SCD is upregulated in many cancers, including androgen receptor (AR)+ LNCaP prostate cancer cells, ErbB2-driven breast cancer cells, pancreatic cancer cells, glioblastoma cells, non-small-cell lung cancer patient samples (NSCLC), and gastric cancer cells." (PMID 38610991, 2024). "Triple-negative breast cancer is more likely to recur than the other two subtypes, with 85% 5-year breast cancer-specific survival for stage I triple-negative tumors vs. 94% to 99% for hormone-receptor-positive and ERBB2-positive types." (PMID 39194688, 2024). "Among 44,293 breast cancers in the FMI Insights database, ERBB2 amplification is at 8% and ERBB2 sequence mutation at 2.9%." (PMID 38335502, 2024). "Improvements in the therapy of ERBB2+ breast cancer have led to extended survival in patients with advanced disease, but the prevention and treatment of central nervous system metastases still pose unique clinical challenges." (PMID 38638322, 2024). "Our data also reveal some unanticipated results, such as the high level of ecDNA found in HER2+ breast cancer (39.3–53.7%), including amplification of ERBB2 on ecDNA in 26% of HER2+ breast cancers." (PMID 39506150, 2024).
breast cancer (continued). "Taken together, these data confirm that ErbB2+ breast cancer cells rely on the uptake and oxidation of FAs for energy production and argue that, of the three isoforms of Cpt1, Cpt1a is primarily responsible for regulating FAO in this context." (PMID 39097623, 2024). "Studies have linked ERBB2 amplifications detected by NGS to the effects of trastuzumab, pertuzumab, and lapatinib in breast cancer." (PMID 38893219, 2024). "These datasets included genes differentially expressed in HER2-E breast cancer compared to Luminal breast cancer, gene sets coexpressed with ERBB2, and transcription factors potentially regulating ERBB2." (PMID 38339428, 2024). "Approximately 30% of breast cancers test positive for human epidermal growth factor receptor 2 (HER2), previously known as HER2/neu or ERBB-2." (PMID 38256428, 2024). "Breast cancer is a significant global health concern, with the overexpression of human epidermal growth factor receptor 2 (HER2/ERBB2) being a driver oncogene in 20%–30% of cases." (PMID 38638322, 2024). ": ERBB2 gene amplification leading to Her2 overexpression occurs in 10–15% of breast cancer, the majority of which are NST carcinomas." (PMID 38015260, 2024). "Specifically, in the diagnosis of early‐stage HER2‐positive breast cancer, NGS techniques can not only validate IHC results but also assist in identifying patients with ERBB2 activating mutations." (PMID 38895905, 2024). "Her2 (ERBB2), a member of the Her family of tyrosine kinase receptors (Her1-4), is a major driver of tumor growth in 20% of breast cancers." (PMID 38380359, 2024). "The effects of BPA on ErbB2/neu-driven breast cancer cell survival were investigated in vitro using TUBO cells, a cell line previously established from a BALB–neuT mouse breast carcinoma, and SRB assay." (PMID 38892447, 2024). "The findings reported herein further demonstrate that chronic exposure to BPA at low doses can participate in ErbB2/neu-driven mammary tumor progression by acting on the tumor immune microenvironment." (PMID 38892447, 2024). "In breast cancer, fibroblast-driven retinoid signaling seems to stimulate tumor progression, as indicated by studies conducted in mouse models of ErbB2-induced mammary tumors." (PMID 38360674, 2024). "In ErbB2-induced mammary tumors, RARβ was found expressed in a subpopulation of myofibroblasts and its loss dampens their expansion and activity." (PMID 38360674, 2024). "One analysis of primary breast cancer samples revealed that ERBB2, FGFR1, MYC, CCND1, and PIK3CA were commonly amplified, and other well-known oncogenes such as CCND2, EGFR, FGFR2, and NOTCH3 were amplified at lower frequencies." (PMID 38611020, 2024). "For instance, cancer regions can be identified by the over-expression of specific genes like ERBB2 in human epidermal growth factor receptor 2 (HER2)-positive breast cancer." (PMID 38947920, 2024). "Coamplification of the CDK12 and ERBB2 genes has previously only been reported in NST breast carcinomas; this study reports this finding for the first time in lobular breast carcinoma." (PMID 38335502, 2024). "In over 20% of breast carcinomas, the ERBB2 gene is amplified leading to overexpression of human epidermal growth factor receptor 2 (HER2), which is associated with poor prognosis." (PMID 39138287, 2024). "In agreement with our results, deletion of the Itgβ4 signaling domain in a mouse model of Erbb2-induced mammary carcinoma resulted in impaired tumor formation." (PMID 38835038, 2024). "We are the first to show that ERBB2‐amplified invasive lobular carcinomas similarly to ERBB2‐amplified NST breast carcinomas do exhibit concomitant CDK12/ERBB2 gene amplification." (PMID 38335502, 2024). "Erythroblastic oncogene B (ERBB2) has been identified as a marker for pancreatic malignancies, breast carcinomas, and gastric cancers." (PMID 39113883, 2024).